TRAV4 (T cell receptor alpha variable 4)
Description:
V region of the variable domain of T cell receptor (TR) alpha chain that participates in the antigen recognition. Alpha-beta T cell receptors are antigen specific receptors which are essential to the immune response and are present on the cell surface of T lymphocytes. Recognize peptide-major histocompatibility (MH) (pMH) complexes that are displayed by antigen presenting cells (APC), a prerequisite for efficient T cell adaptive immunity against pathogens. Binding of alpha-beta TR to pMH complex initiates TR-CD3 clustering on the cell surface and intracellular activation of LCK that phosphorylates the ITAM motifs of CD3G, CD3D, CD3E and CD247 enabling the recruitment of ZAP70. In turn ZAP70 phosphorylates LAT, which recruits numerous signaling molecules to form the LAT signalosome. The LAT signalosome propagates signal branching to three major signaling pathways, the calcium, the mitogen-activated protein kinase (MAPK) kinase and the nuclear factor NF-kappa-B (NF-kB) pathways, leading to the mobilization of transcription factors that are critical for gene expression and essential for T cell growth and differentiation. The T cell repertoire is generated in the thymus, by V-(D)-J rearrangement. This repertoire is then shaped by intrathymic selection events to generate a peripheral T cell pool of self-MH restricted, non-autoaggressive T cells. Post-thymic interaction of alpha-beta TR with the pMH complexes shapes TR structural and functional avidity.
Synonyms: TCRAV20S1; TCRAV4S1
Gene: T-cell receptor variable (V) gene on chromosome 14 (21,736,152 to 21,736,982, forward strand). Ensembl gene ENSG00000211778.
Subcellular location: Cell membrane
Gene Ontology:
Biological process: response to bacterium
Cellular component: plasma membrane
Homologues: Orthologues: pig TRAV4 (73% identical), rat Trav2 (72% identical), mouse Trav2 (72% identical), rabbit TRAV4 (69% identical). Paralogues in human: TRAV26-1 (59% identical), TRAV26-2 (50% identical), TRAV21 (26% identical), TRAV39 (26% identical), TRAV38-1 (25% identical), TRAV38-2DV8 (25% identical), TRAV13-1 (24% identical), TRAV20 (24% identical), TRAV1-1 (23% identical), TRAV10 (23% identical), TRAV17 (23% identical), TRAV30 (23% identical), and 11 more.
Diseases named in the same sentence as TRAV4 in open-access papers:
TRAV4 is named in the same sentence as 3 diseases in open-access papers, as found by Europe PMC text mining. Sharing a sentence is not in itself a finding about the gene and the disease. The quoted sentences say what the papers report.
adenocarcinoma (1 paper, 2023). A common cancer characterized by the presence of malignant glandular cells. "Furthermore, TRAV4, which encodes T-cell receptor alpha variable 4, and JCHAIN, which encodes Ig J Chain, have been reported to be related to adenocarcinoma." (PMID 37762221, 2023).
tumour (1 paper, 2018). "Here we show that the structures of two distinct TCRs (TRAV4+TRAJ21+-TRBV28+TRBJ2-3+ and TRAV4+TRAJ8+-TRBV9+TRBJ2-1+), originating from a polyclonal T-cell repertoire, bind to HLA-B*07:02, presenting a 13-amino-acid-long tumour-associated peptide, NY-ESO-160–72." (PMID 29531227, 2018).
TRAV4 also shares sentences with these, for which no sentence is quoted: COVID-19 (1 paper).